GABRA5 (gamma-aminobutyric acid type A receptor subunit alpha5)
Diseases named in the same sentence as GABRA5 in open-access papers:
GABRA5 is named in the same sentence as 55 diseases in open-access papers, as found by Europe PMC text mining. Sharing a sentence is not in itself a finding about the gene and the disease. The quoted sentences say what the papers report.
autism (17 papers, 2013 to 2025). Persistent deficits in social interaction and communication and interaction as well as a markedly restricted repertoire of activity and interest as well as repetitive patterns of behavior. "In mice, sevoflurane exposure induced autism-like behaviours and led to the downregulation of high-risk autism genes, including ARID1B, GABRA5, GABRB3, GRIN2B, SHANK3 and SUV420H1." (PMID 39372140, 2024). "15q11–q13 site contains coding regions of specific subunits of GABA-AR, including GABRB3, GABRA5, and GABRG3, which are strongly implicated in the pathogenesis of autism." (PMID 35198562, 2021). "Focusing on just the top 1% in the two validation datasets, given their high correlation, we identified several other genes that have been implicated in autism and synaptic transmission including GABRA3, GABRA5 and GABRB1, all of which encode subunits of the GABA receptor." (PMID 29483624, 2019). "Individuals with autism had notably lower levels of EAAT2, KCC2, NKCC1, VD3, GABA, and GABRA5, especially in the severe group." (PMID 40330649, 2025). "A recent study reported widely decreased expression of genes encoding different subunits of GABA-AR, including GABRA1, GABRA2, GABRA3, GABRB3, GABBR1, and GABBR2, which is consistent with an earlier study reporting reduced GABRA1, GABRA5, and GABRB2 levels in the cortex of VPA-induced autism models." (PMID 35198562, 2021).
epilepsy (11 papers, 2016 to 2024). A brain disorder characterized by episodes of abnormally increased neuronal discharge resulting in transient episodes of sensory or motor neurological dysfunction, or psychic dysfunction. "The GABRA5 gene encodes the α5 subunit of the GABAA receptor, and mutations in GABRA5 have been associated with epilepsy." (PMID 38539663, 2024). "Additionally, many studies suggest that deficits in the GABAA receptors such as GABRA2 and GABRA5 contribute to central nervous system disorders such as anxiety disorders, epilepsy, schizophrenia, and insomnia." (PMID 37355705, 2023). "They observed that six (5.9%) patients with functional seizures (without comorbid epilepsy) carried pathogenic/likely pathogenic variants (deletions at 10q11.22-q11.23, 10q23.1-q23.2, distal 16p11.2, and 17p13.3, and nonsynonymous variants in NSD1 and GABRA5)." (PMID 37628589, 2023). "We observe in this first genetic investigation of PNES that six (5.88%) individuals with PNES without coexistent epilepsy carry P/LP variants (deletions at 10q11.22-q11.23, 10q23.1-q23.2, distal 16p11.2, and 17p13.3, and nonsynonymous variants in NSD1 and GABRA5)." (PMID 32938993, 2020). "We found that variants in the epilepsy-associated genes GABRA1, GABRB3 and GABRG2 were mainly present in the ESP variants, but the GEC cohort contained epilepsy-associated GABRA6, GABRB1, and GABRB2 and non-epilepsy- associated GABRA4, GABRA5, and GABRG3 genes." (PMID 27622563, 2016).
Angelman syndrome (7 papers, 2016 to 2025). A neurogenetic disorder characterized by severe intellectual deficit and distinct facial dysmorphic features. "Perturbations in the GABRA5 gene, encoding the α5 subunit, were found in patients with panic disorder, and heterozygous expression of the gene is commonly present in patients with Angelman syndrome, where anxiety and autism are commonly reported conditions." (PMID 36833213, 2023). "Polymorphic Tandem Repeat (PTR) at the GABRA5 locus have been described, including both deletions and duplications in the 15q11-q13 region, known to be methylated in Prader Willi and Angelman syndromes (MIM, 176,270; MIM, 105,830)." (PMID 38992676, 2024). "GABRA5 is a gene frequently missing from the maternal chromosome in Angelman syndrome patients that harbor a large deletion ranging from 4–6 Mb." (PMID 36833213, 2023). "In Angelman syndrome, a disorder highly penetrant for ID, beta power is reduced in cases caused by 15q11-q13 deletion relative to cases with etiologies that mainly impact UBE3A, suggesting a positive relationship between beta power and GABRB3/GABRA5/GABRG3 copy number." (PMID 31312421, 2019).
schizophrenia (6 papers, 2012 to 2023). A major psychotic disorder characterized by abnormalities in the perception or expression of reality. "Gamma-aminobutyric acid type A receptor subunit Alpha 5 (GABRA5) was linked to schizophrenia, mood disorders, alcoholic intoxication, and bipolar disorders." (PMID 37252132, 2023). "GABRA5 mRNA levels were unchanged when comparing the high versus low inflammatory schizophrenia subgroups." (PMID 34174930, 2021). "Furthermore, the dissimilarities between the symptoms of schizophrenia and those observed so far in the Gabra1 and Gabra5 knockouts suggest that the extensive similarities between Gabrb2 knockout and schizophrenia are not readily shared by knockouts of other subunits of GABAA receptors." (PMID 30013074, 2018). "We sought to determine relative levels of GABRA1, GABRA2, GABRA3, and GABRA5 mRNAs, GABRA3 protein levels, and to determine cellular location of GABRA3 protein in the midbrain in schizophrenia." (PMID 34174930, 2021).
Anxiety (5 papers, 2018 to 2023). Intense feelings of nervousness, tension, or panic often arise in response to interpersonal stresses. "Based on reports from patients with impairments in the GABRA5 gene and animal studies with allosteric modulators to the α5 subunit, we were expecting to see an increase in anxiety-like behavior in our Gabra5−/− model." (PMID 36833213, 2023). "Taken together, these findings make the Gabra5 gene an interesting candidate for studies on glucocorticoids and anxiety-like behavior." (PMID 36833213, 2023). "Altogether, we observed decreased corticosterone levels in Gabra5−/− mice and decreased rearing behavior, suggesting lower anxiety levels as well as hyperpolarization of pyramidal hippocampal neurons in α5 deletion neurons." (PMID 36833213, 2023). "Our patient with PNES and a GABRA5 mutation had normal neurodevelopment, an onset of PNES at 40 years of age, a history of mood disorder, anxiety, and PTSD, and no history of febrile seizures or family history of seizures." (PMID 32938993, 2020). "For example, the human GABRA5 and GABRB3 are located in the 15q11.2-q13 region, and maternal duplications of 15q11.2-q13 leads to neurodevelopmental disorders including ASD, and their clinical symptoms often include anxiety, emotional lability, tantrums, and hyperactivity." (PMID 29391390, 2018).
bipolar disorder (5 papers, 2007 to 2023). A disorder of the brain that causes unusual shifts in mood, energy, activity levels and the ability to carry out day-to-day tasks. "Linkage studies have identified a susceptibility locus within the GABRA5 gene (15q11-q13) for bipolar depression." (PMID 27920723, 2016). "We identified the up-regulation of gamma-amino butyric acid A receptor, α5 (GABRA5) subunit gene in suicide associated with bipolar disorder, confirming a previous report." (PMID 17997842, 2007). "In the ACC and dlPFC, data suggest that expression of the GABRA5 gene is increased in cortical layers 2–6 of subjects with bipolar depression and those with MDD." (PMID 27920723, 2016).
depression (4 papers, 2014 to 2022). "Post-mortem studies have further examined the link between GABRA5 gene expression and depression, with mixed findings." (PMID 27920723, 2016).
medulloblastoma (4 papers, 2014 to 2024). A malignant, invasive embryonal neoplasm arising from the cerebellum. "The GABRA5 gene, which encodes the α5 subunit of the GABAA receptor, has been implicated in an aggressive subgroup of medulloblastoma (MB), a type of pediatric brain tumor." (PMID 38539663, 2024). "The expression of GABRA5, which encodes the α 5-GABAA receptor, has a synthetic lethal role in MYC-driven medulloblastoma." (PMID 36105089, 2022). "Also, increased levels of GABRA5 were described in the most aggressive molecular subgroup, namely Group 3, of medulloblastoma (MB), the main type of malignant brain cancer afflicting children." (PMID 38539663, 2024). "Some individual members of these pathways, including GNB3, GNB5, GABRA5, RCVRN and SAG were exclusively over-expressed in Group 3 medulloblastoma." (PMID 25412507, 2014).
breast carcinoma (3 papers, 2022 to 2025). "We found that the seven GABAA receptor subunits were upregulated in TNBC breast cancers, including GABRA1, GABRA5, GABRD, GABRE, GABRP, GABRQ, and GABRG3." (PMID 36923530, 2023). "Among these six genes, five were hypermethylated (GABRA5, ZIC5, GRAMD4, RSPH3, and VCAN), and one was hypomethylated (CSMD1) in breast cancer samples of cases compared to controls." (PMID 36627894, 2022).
epileptic encephalopathies (3 papers, 2023 to 2024). "GABRA5 (γ-Aminobutyric Acid Type A Receptor Subunit Alpha5) influences inhibitory activity; so far, diseases that have been associated with this gene include epileptic encephalopathies." (PMID 37628589, 2023). "Finally, mutations in both Gabra1 and Gabra5 genes, which are dysregulated in our mice, leading to functional hypoactivity of the GABAergic system, are associated with the genetic etiology of both benign and severe epilepsy syndrome and early-onset epileptic encephalopathies." (PMID 39583831, 2024).
Alzheimer disease (2 papers, 2022). A progressive, neurodegenerative disease characterized by loss of function and death of nerve cells in several areas of the brain leading to loss of cognitive function such as memory and language. "Interestingly, GABRA5 overexpression was described in different brain areas of Alzheimer's disease mouse model, and it was associated with a gamma-aminobutyric acid activation–dependent cell death, provoked by mitochondrial oxidative stress." (PMID 35835219, 2022).
anxiety disorder (2 papers, 2023). A category of psychiatric disorders which are characterized by anxious feelings or fear often accompanied by physical symptoms associated with anxiety. "In this study, we investigated the relationship between the α5 subunit and corticosterone levels in a new mouse model deficient for Gabra5, which is known to be linked to anxiety disorders in humans and phenologs observed in mice." (PMID 36833213, 2023).
autism spectrum disorder (2 papers, 2017 to 2021). A spectrum of developmental disorders that includes autism, and Asperger syndrome. "GABAA receptor subunit genes GABRB3, GABRA5, and GABRG3 located on chromosome 15q11-q13 have been implicated in the etiology of autistic spectrum disorders (ASD)." (PMID 28607477, 2017).
glial tumors (2 papers, 2009 to 2015). "The lowest GABRA5 mRNA levels were found in glioblastoma compared to gliomas of lower malignancy, which is consistent with the remarkable decrease in GABRA5 expression." (PMID 25845910, 2015). "Furthermore, DEGs exclusively detected at grade IV with large FC values (i.e., IGFBP2 and GABRA5) revealed huge variation in expression levels compared to previous grades, which was speculated to be closely correlated with the significant changes during the development of glioma into glioblastoma." (PMID 25845910, 2015).
idiopathic generalized epilepsy (2 papers, 2022 to 2023). A generalised epilepsy that encompasses several common seizure phenotypes including childhood absence epilepsy, juvenile absence epilepsy, juvenile myoclonic epilepsy and epilepsy with generalized tonic-clonic seizures alone. "Previous studies have shown that mutations of the GABA receptors, such as, GABRA1, GABRA5, GABRA6, GABRB3, GABRD, GABRG2, were associated with idiopathic generalized epilepsy." (PMID 35663265, 2022).
memory impairment (2 papers, 2011 to 2013). "Thus, this study has revealed, for the first time, that long-term of ketamine administration and associated memory impairments may be related to an up-regulation of Gabra5 subunits in the prefrontal cortex." (PMID 21712993, 2011). "Additionally, Gabra5−/−mice exhibit a reduced sensitivity to memory impairment by etomidate, which potently enhances the activity of α5GABAA receptors." (PMID 23516534, 2013).
thymoma (2 papers, 2022 to 2024). A neoplasm arising from the epithelial cells of the thymus. "A development of atypical immune microenvironments in the thymus with germinal center formation, B cell maturation, and ectopic neuromuscular expression of GABRA5, MAP2, NEFL, NEFM, SOX15 by neuromuscular mTECs (KRT6+ GABRA5+ nmTECs) was described for MG-associated thymomas." (PMID 38571951, 2024). "Single-cell RNA-seq and immunohistological examination of MG-type thymoma specimens revealed that these neuromuscular expressions were limited in a subpopulation of mTECs (GABRA5+KRT6+), termed nmTECs." (PMID 35869073, 2022). "To verify the predicted interaction, we performed immunostaining of CD31 on MG-type thymoma sections and observed that GABRA5+ nmTECs were in proximity to CD31+ vascular endothelial cells." (PMID 35869073, 2022). "To quantify the amount of nmTECs, we performed immunostaining for GABRA5 and found that the number of GABRA5-positive cells was higher in MG (P = 0.050) and more significantly in anti-AChR antibody-positive thymoma patients (P = 4.2 × 10−4)." (PMID 35869073, 2022).
alcohol dependence (1 paper, 2021). Physical and psychological dependence on alcohol. "A significant association between alcohol dependence and the GABAA receptor genes GABRB3 and GABRA5 was also revealed in a family-based association study in the Caucasian population." (PMID 34530807, 2021).
cholangiocarcinoma (1 paper, 2018). A carcinoma that arises from the intrahepatic biliary tree (intrahepatic cholangiocarcinoma) or from the junction, or adjacent to the junction, of the right and left hepatic ducts (hilar cholangiocarcinoma). "This strong correlation was confirmed by analyzing gene expression data from cholangiocarcinomas present in the cancer genome atlas (TCGA), suggesting that taurine signaling through GABRA5 prolongs survival by suppressing cell proliferation." (PMID 29787571, 2018). "To correlate taurine signaling and proliferation, we determined GABRB3, GABRA5 and Ki67 protein levels in 7 cholangiocarcinoma samples by immunohistochemical staining (IHC)." (PMID 29787571, 2018). "In all samples GABRB3 was reduced or completely lost in tumor cells, whereas GABRA5 protein was reduced in part of the neoplastic ductular structures in 3 out of 7 cholangiocarcinoma samples." (PMID 29787571, 2018). "Stratifying the cohort of 104 cholangiocarcinomas for RNA expression above and below the mean revealed that low RNA expression of GABRA5, LRRC8a, ADO and PANK1, but not GABRB3, was associated with reduction of the median survival time of patients by 1.8, 2.1, 3.3, and 4.3 years, respectively." (PMID 29787571, 2018). "Microarray-based expression profiling of 104 resected human cholangiocarcinomas revealed reduced expression of GABRB3, PANK1, and LRRC8A, but not GABRA5 or ADO, compared to micro-dissected bile duct controls." (PMID 29787571, 2018).
Cognitive impairment (1 paper, 2022). Abnormal cognition is characterized by deficits in thinking, reasoning, or remembering. "In this study, GABRA5 was found to be involved in diabetes-related cognitive impairment as one of the core target proteins of the Shunaoxin pill, which may be related to its high expression in the hippocampus." (PMID 36341127, 2022). "Active ingredients of the Shunaoxin pill may alleviate cognitive impairment in diabetic patients by targeting the proteins OPRK1, GABRA5, GABRP, and SCN3B." (PMID 36341127, 2022).
colon cancer (1 paper, 2024). "However, irrespective of whether expression of GABAA or GABAB receptor subunits were altered in colon cancer, expression of particular receptor subtypes (GABRA1, GABRA5, GABRD, GABRE, GABRG1, GABRG3, GABBR1, and GABBR2) was significantly associated with poor clinical outcome." (PMID 38886975, 2024).
encephalopathies (1 paper, 2025). "The genes NDN, SNRPN, and UBE3A are known for their association with Prader–Willi syndrome; GABRB and GABRA5 are associated with encephalopathies; OCA2 and HERC2 are linked to skin pigmentation." (PMID 40149731, 2025).
meningioma (1 paper, 2017). A generally slow growing tumor attached to the dura mater. "NME1, NFE2, SFN, PTN, CALN1, GABRA5 and several components involved in neural differentiation and receptors associated with neural transmitter were also found to illicit an autoimmune response in the meningioma patients indicating that there could be some alterations in these components." (PMID 28938569, 2017).
mental disorder (1 paper, 2022). A disease that has its basis in the disruption of mental process. "The core targets of SHR during the treatment of mental disorders were GABRA1, GABRA2, GABRA3, GABRA5, and GABRA6, involving synaptic transmission and transmembrane movement." (PMID 39280954, 2022).
Prader-Willi syndrome (1 paper, 2019). "In the future, we will examine Prader Willi syndrome to further disentangling the electrophysiological roles of UBE3A and GABRB3/GABRA5/GABRG3." (PMID 31312421, 2019).
tumor (5 papers, 2018 to 2025). "Low GABRA5 expression typified hyperproliferative tumors, and loss of taurine signaling correlated with reduced patient survival, suggesting this tumor suppressive mechanism operates in vivo." (PMID 29787571, 2018). "Two sets of genes were chosen, PDGFRA, Lin28A, THBS1, JUN, PLCB1 and GABRA5, which were found to be up- and down-regulated, respectively, in support of tumour cell proliferation." (PMID 38000389, 2024). "For example, low GABRA expression is characteristic of hyperproliferative tumours, and higher GABRA5 expression has been shown to inhibit or slow tumour proliferation." (PMID 38000389, 2024). "GABRA5 and the α5 subunit are found and contribute to the assembly of functional GABAA receptors in patient-derived Group 3 MB cells and tumor tissue." (PMID 38539663, 2024).
cancer (3 papers, 2012 to 2018). A tumor composed of atypical neoplastic, often pleomorphic cells that invade other tissues. "We may hypothesize that the increase of GABRA5 expression observed can promote cancer development; however, further analyses are needed." (PMID 25755686, 2015).
psychiatric disorder (3 papers, 2020 to 2022). A disorder characterized by behavioral and/or psychological abnormalities, often accompanied by physical symptoms. "The next three P/LP variants (one P, two LP) were identified in two genes and at a chromosomal position, each implicated in neurological or psychiatric disorders with or without seizures (NSD1, 10q11.22-q11.23 deletion, and GABRA5)." (PMID 32938993, 2020).
movement disorder (1 paper, 2025). Neurological conditions resulting in abnormal voluntary or involuntary movement, which may impact the speed, fluency, quality and ease of movement. "Rescued XDP signature genes such as GABRA5, STX6, and ATP6V0A1 code for subunits of channels or receptors that map to glutamatergic or GABAergic synapses, cellular components that are relevant for neurotransmission and the movement disorder phenotype observed in XDP." (PMID 41282719, 2025).
GABRA5 also shares sentences with these, for which no sentence is quoted: neurodevelopmental disorder (3 papers); mood disorder (2); adenocarcinoma (1); brain tumor (1); central nervous system disorder (1); deafness (1); developmental and epileptic encephalopathy (1); endometrial cancer (1); epilepsy syndrome (1); fragile X syndrome (1); glioblastoma (1); gliomas (1); hearing loss (1); ischemia (1); learning disabilities (1); lung adenocarcinoma (1); myasthenia gravis (1); myopia (1); neuroblastoma (1); neurodegenerative disease (1); neurological disorders (1); non-small cell lung carcinoma (1); panic disorder (1); pilocytic astrocytoma (1); substance abuse (1); tuberous sclerosis (1).